NLRP3 (NLR family pyrin domain containing 3)
Diseases named in the same sentence as NLRP3 in open-access papers (continued):
Sharing a sentence is not in itself a finding about the gene and the disease.
gout (continued). "Taken together, these data suggest that Z1456467176 blocks the NLRP3-IL-1β pathway by inhibiting BzATP-induced P2X7R activation in gout patients in vitro." (PMID 36052144, 2022). "Then, selected natural products reported in the literature as NLRP3 inhibitors will be discussed, with a particular focus in some which target gout." (PMID 36234744, 2022). "An NLRP3 inhibitors (Dapansutrile) has shown promising results against gout flares in early clinical trials." (PMID 35438238, 2022). "In the present study, we demonstrated that allosteric regulation of P2X7R to inhibit the NLRP3 inflammasome effectively alleviates gout inflammation, providing theoretical and data support for P2X7R as a therapeutic target for gout." (PMID 36052144, 2022). "In this study, we examined the effect of PIP in immunosuppression of gout inflammation through the regulation of the NLRP3 inflammasome." (PMID 35400961, 2022). "Mitochondrial dysfunction can induce the NLRP3 inflammasome in gout to promote IL-1β and inflammation." (PMID 35813212, 2022). "Although previous studies have shown that MSU-induced inflammation is closely related to the activation of the NLRP3 inflammasome, the role of pyroptosis in the pathogenesis of gout remains controversial." (PMID 36142364, 2022). "Several existing natural ingredients and artificial pharmacological inhibitors improve gout by directly inhibiting the assembly or activation of the NLRP3 inflammasome." (PMID 35464445, 2022). "NLRP3 is involved in hereditary Cryopyrin-associated periodic syndromes, such as Muckle–Wells syndrome, diabetic retinopathy, colorectal inflammatory disease, and gouty arthritis; treatment with NLRP3 inhibitors has been reported in these diseases." (PMID 35351143, 2022). "Here, we review selected natural products reported in the literature as NLRP3 inhibitors, with a particular focus on those targeting gout." (PMID 36234744, 2022). "First, we explored the role of pyroptosis in gout, in which the assembly of NLRP3, a key molecule in pyroptosis, is considered a critical step in the progression from hyperuricemia to gout." (PMID 35464445, 2022). "Collectively, these results demonstrated that corilagin suppressed the ROS/TXNIP/NLRP3 pathway to repress inflammasome activation and pyroptosis and suggest its potential antioxidative role in alleviating NLRP3-dependent gouty arthritis." (PMID 36299604, 2022). "Here we show that POP1 inhibits uric acid crystal-induced NLRP3 inflammasome activation, inflammation and ameliorates gout in a mouse model." (PMID 36225929, 2022). "Similar to RA patients, the serum and synovial fluid samples of the patients with gout were detected to contain higher levels of NLRP3, caspase-1, IL-1β, and IL-18." (PMID 35629398, 2022). "The NLRP3 inflammasome is a multiprotein complex identified as a mediator with an important role in the inflammation of gouty arthritis." (PMID 35400961, 2022). "On the other hand, βArr2 has been shown to inhibit NLRP3 inflammasome in inflammatory disorders such as Parkinson’s disease and gout." (PMID 34787064, 2022). "Monosodium urate (MSU) crystals are both potent NLRP3 inflammasome inducers as well as mediators of other inflammatory diseases such as gout." (PMID 35246034, 2022). "Direct inhibition of the NLRP3 inflammasome as an alternative approach to targeting IL-1β reduces the inflammatory response in gout." (PMID 36142890, 2022). "Dapansutrile has been shown to be safe in humans, and Dapansutrile was the first NLRP3 inhibitor to complete two human proof-of-concept studies, one for acute gouty arthritis flares (Phase 2a) and one for stable systolic heart failure (NYHA II-III) (Phase 1b)." (PMID 36105284, 2022). "It is also known that several polymorphisms in inflammasome-related genes (NLRP3, IL-1β, CARD8) are associated with a greater risk of developing gout." (PMID 35629398, 2022).
gout (continued). "Gout, a developed form of hyperuricemia, is usually characterized by persistent low-grade inflammation, since the crystalline urate can activate the NLRP3 inflammasome and contribute to IL-1β activation." (PMID 36245501, 2022). "We assume that the CM from LPS-primed and MSU-treated inflammatory phenotype macrophages mimic the effect of gout-activation of NLRP3 inflammsome in macrophages on cardiomyocytes in vitro." (PMID 35368226, 2022). "Recent studies have confirmed that the NLRP3 inflammasome is activated during the onset of gouty arthritis." (PMID 36569836, 2022). "Current studies suggest that innate immunostimulatory activity, especially the MSU crystals-mediated NLRP3 inflammasome activation plays a vital role in gouty arthritis development." (PMID 35464862, 2022). "When the quail showed gout symptoms, the NLRP3 inflammasome was activated, and the expressions of IL-1β, TNF-α, IL-6, IL-8, and IL-18 were significantly increased." (PMID 36569836, 2022). "For example, miR-223-3p and miR-22-3p reduce the production of IL-1β by targeting NLRP3, thereby alleviating the inflammatory response of gout." (PMID 36339582, 2022). "Our previous research revealed that compounds derived from traditional Chinese medicine display potential therapeutic effects on NLRP3-dependent gouty arthritis." (PMID 36299604, 2022). "The production of inflammatory mediators by leukocytes modulated by the NLRP3 inflammasome auto-amplifies necroinflammation, thereby contributing to the progression of gouty arthritis." (PMID 35400961, 2022). "The immune response between uric acid metabolism targets XOD and NLRP3 inflammasomes and plays a crucial role in developing treatments for overnutrition-induced gout." (PMID 36569836, 2022). "Based on the release of extracellular ATP after MSU crystal stimulation, these data suggest that Z1456467176 effectively alleviates the symptoms of gouty arthritis by acting on P2X7R to inhibit ATP-induced activation of the NLRP3 inflammasome." (PMID 36052144, 2022). "A previous study also showed that caffeic acid, β-carotene and sulforaphane modulate inflammation by acting as selective and direct inhibitors of the NLRP3 inflammasome in MSU-induced gout mice." (PMID 35370689, 2022). "Reduce ROS levels and inhibit MSU-induced NLRP3 inflammasome activation in the mouse macrophage line RAW264.7 to improve gout pain." (PMID 35464445, 2022). "The oral administration of PIP in both protocols demonstrated the immunosuppressive activity of PIP associated with NLRP3 inflammasome inhibition and suppression of the pathogenesis of MSU-induced gout (Figure-3)." (PMID 35400961, 2022). "Purine metabolism disorder causes urate accumulation to form MSU crystals, which can drive NLRP3 inflammasome oligomerization and IL-1β release and triggers acute gouty arthritis flares." (PMID 36299604, 2022). "Collectively, this study confirms that the increased XOD activity, ROS expression, and NLRP3 inflammasome play an essential role in inflammasome dysregulation and triggers gout." (PMID 36569836, 2022). "An ABCG2 SNP (rs2231142) enhances this autophagic impairment, diminishes the formation of neutrophil extracellular traps, and aggravates gout via the overactive release of the NLRP3 inflammasome and IL-1β." (PMID 35813212, 2022). "Our results illustrate that corilagin restricts ROS/TXNIP/NLRP3 pathway to diminish macrophage pyroptosis and proinflammatory cytokines release, thereby alleviating NLRP3-dependent gouty arthritis." (PMID 36299604, 2022). "The NLRP3 levels of patients with alcoholic liver injury and gouty arthritis were significantly increased, indicating that NLRP3 inflammasome was activated in alcoholic liver injury and gouty arthritis." (PMID 36176434, 2022). "We identified that reminiscent to POP2, also POP1 inhibits uric acid crystal-induced NLRP3 inflammasome activation and ameliorates gout." (PMID 36225929, 2022).
gout (continued). "In vivo and in vitro studies, Z1456467176 inhibited ATP- or BzATP-induced P2X7R activation to block the NLRP3-caspase-1-IL-1β pathway, alleviating the clinical manifestations of gouty arthritis and confirming P2X7R as an effective therapeutic target." (PMID 36052144, 2022). "The NOD-like receptor protein 3 inflammasome (NLRP3) aggravated the pathological conditions of numerous arthritis, including OA and gouty arthritis, by generating proinflammatory cytokine." (PMID 36552524, 2022). "In this regard, the NLRP3 inflammasome is known to play a crucial part and thus has been proposed as a novel target in the treatment for gout." (PMID 35370689, 2022). "Together, these results demonstrated that GPS is able to attenuate gouty arthritis via inhibiting NLRP3 inflammasome activation." (PMID 34586567, 2022). "When the NLRP3 inflammasome is overactivated, many inflammatory factors are formed, triggering an inflammatory response in vivo and promoting gout development." (PMID 36569836, 2022). "Further, 8A alleviated lipopolysaccharide-induced endotoxemia, as well as monosodium urate-induced peritonitis and gouty arthritis in mice by suppressing NLRP3 inflammasome activation." (PMID 36379253, 2022). "A similar observation was previously made using an NLRP3 inhibitor in a gout model, which also suppressed IL-6 and CXCL1 in synovial tissue after MSU crystal injection." (PMID 36225929, 2022). "Here, we provide selected examples of natural products (NPs) that have been reported in the literature as NLRP3 inhibitors, with a focus on those relating to gout." (PMID 36234744, 2022). "The results of this study also confirmed that XOD plays an essential role in the development of gout, which can elevate uric acid levels, promote the release of ROS and activate the NLRP3 inflammasome." (PMID 36569836, 2022). "CY-09, an analog of cystic fibrosis transmembrane conductance regulator (CFTR) inhibitor-172 (C172), blocks ATP binding with NLRP3 by directly binding to the NLRP3 Walker A motif, showing protective effects in mice models of gout and Types 2 diabetes." (PMID 35741054, 2022). "Acute gout attacks depend on not only activation of the NLRP3 inflammasome but also upregulation of IL-1β transcription." (PMID 36339582, 2022). "The aberrant activation of NLRP3 inflammasome was found in many human diseases, including Alzheimer’s diseases, type 2 diabetes, and gout." (PMID 35879806, 2022). "An important feature of gouty arthritis is the activation of NLRP3 inflammasome and the release of IL-1β." (PMID 33505510, 2021). "An acute gout flare is conditioned not only on activation of NLRP3 inflammasomes but also on upregulation of IL1B transcription." (PMID 34246297, 2021). "MSU crystals induce the activation of the NLRP3 inflammasome and subsequent release of mature IL-1β, contributing to the development and progress of gouty arthritis." (PMID 33670601, 2021). "While the activation of IL-1β and the role of NLRP3 in gout have been relatively well-established, the upstream pathways involved in MSU-triggered NLRP3 activation are not yet fully understood." (PMID 33926105, 2021). "Recognition of the importance of NLRP3 inflammasome activation and bioactive IL-1β release in the initiation of gout flares has led to the development of antiIL-1β biological therapy for gout flares." (PMID 34721647, 2021). "The etiology of gout is directly linked to the NLRP3 inflammasome, since MSU crystals are NLRP3 inflammasome activators." (PMID 33670601, 2021). "Further research showed that MSU synergizes with ATP to promote NLRP3 inflammasome activation and gout flare." (PMID 34150848, 2021). "In a Wistar rat model of MSU-evoked gouty arthritis, curcumin produced salutary effects by inhibiting NLRP3 inflammasome suppression via repression of NF-κB signaling both in vitro and in vivo." (PMID 34443594, 2021).
gout (continued). "The multi-target effect of β-Caryophyllene inhibited the activation of two gout-inflammation pathways screened in our KEGG analysis---the NLRP3 inflammasome and the NF-κB pathway." (PMID 33967792, 2021). "Oridonin, a major active ingredient of Rabdosia rubescens, directly targets NLRP3 to mediate its preventive effects in mouse models of peritonitis, gouty arthritis and type 2 diabetes." (PMID 34603026, 2021). "These indicate that MSU crystals induce mitochondrial stress in macrophages and inflamed gouty tissues, suggesting the involvement of mitochondria dysfunction and consequent NLRP3 inflammasome activation in the pathogenesis of gout." (PMID 33670601, 2021). "Many other flavonoids are reported to exert anti-inflammatory effects on mouse models of gouty arthritis, inhibiting both stages of the NLRP3 inflammatory process." (PMID 33926105, 2021). "A linkage between gout incidence and polymorphisms has been reported in PPARGC1B, which increased NLRP3 and IL-1β expression." (PMID 33926105, 2021). "Some evidence has demonstrated that the MSU crystal-induced inflammatory responses and gout pathogenesis are dependent on NLRP3 inflammasome activation." (PMID 34079466, 2021). "NLRP3 plays an important role in the progression of metabolic disorders, including obesity-induced insulin resistance and the development and severity of gout, nonalcoholic fatty liver disease, and type 2 diabetes." (PMID 34832960, 2021). "Our results show that oral administration of loganin prevented gout inflammation induced by MSU crystals via inhibition of NLRP3 inflammasome activation." (PMID 33670601, 2021). "Tranilast showed beneficial pharmacological effects on NLRP3 inflammasome-associated diseases in animal models of CAPS, type 2 diabetes, and gout)." (PMID 33673188, 2021). "Metastasis associated lung adenocarcinoma transcript 1 suppresses the monosodium urate-induced inflammation via the miR-876-5p/NLRP3 cascade in gouty arthritis." (PMID 34874227, 2021). "Macrophages intake MSU crystals, the trigger for NLRP3 inflammasome activation, which leads to the release of interleukin (IL)-1β and results in the flaring of gout." (PMID 34440688, 2021). "In support of this is the known phenomenon that treatment with thiazides can induce gout, which is triggered by NLRP3 activation." (PMID 34315884, 2021). "Another way of miRNA interference is regulating the expression of genes involved in gout immune response, e.g., miR-223 can suppress NLRP3 expression and reduce inflammasome activity." (PMID 34246297, 2021). "Despite much progress has been made in elucidating the importance of NLRP3 inflammasome in gout pathology, the precise mechanisms through which NLRP3 inflammasome is activated under gout condition remain elusive." (PMID 33785039, 2021). "There many studies on NLRP3 inflammasome and its regulation by miRNAs; it is a key component not only in gout but also in other inflammatory diseases." (PMID 34246297, 2021). "NLRP3 inflammasome activation and the release of IL-1β have essential roles in gout by triggering acute gout flares." (PMID 33534121, 2021). "Up to date, multiple lncRNAs are elucidated to make significant contribution to pathogenesis of gout, for example, HOX transcript antisense RNA knockdown alleviates gouty arthritis by downregulation of NLR family pyrin domain containing 3 (NLRP3)." (PMID 34874227, 2021). "In MSU crystal-induced peritonitis and gouty arthritis in mice, oridonin attenuated the NLRP3 inflammasome-dependent acute inflammatory responses." (PMID 33535473, 2021). "In an open-label phase 2A study in patients with gout, a disease dependent on NLRP3 inflammasome activation, OLT1177 was safe and effective in reducing target joint pain." (PMID 33673188, 2021). "In this line, β-carotene administered orally (30 mg/kg) inhibited NLRP3 inflammasome activation in a model of gouty arthritis in mice, as well as suppressed levels of IL-1β in synovial fluid cells isolated from gout patients." (PMID 34677429, 2021).
gout (continued). "Uric acid crystals (monosodium urate)‐induced pyroptosis functions in the acute gouty arthritis, possibly through regulating the NF‐κB/NLRP3/GSDMD signaling pathway." (PMID 34459122, 2021). "Gouty arthritis is caused by the deposition of MSU crystals in joints, which—remarkably—activate the NLRP3 inflammasome." (PMID 33535473, 2021). "OLT1177® has been shown to be safe in humans, and it became the first NLRP3 inhibitor to complete two human proof of concept studies, one in acute gout flares (Phase 2a) and one in stable systolic heart failure (NYHA II-III) (Phase 1b)." (PMID 34207886, 2021). "In mouse models, Eri had therapeutic effects on peritonitis, gouty arthritis and type 2 diabetes, via NLRP3." (PMID 34745110, 2021). "This discrepancy indicates that more experiments need to be performed to clearly elucidate the role of NLRP3 in MSU crystal-induced gouty arthritis." (PMID 34803702, 2021). "This suggests that loganin suppresses MSU crystals-induced NLRP3 inflammasome activation by blocking mitochondrial damage, culminating in the alleviation of acute gout inflammation derived from MSU crystal deposition." (PMID 33670601, 2021). "The activation of NLRP3 inflammasome releases large amounts of IL-1β is a central process of MSU-mediated gout flares." (PMID 34925366, 2021). "The activation of NLRP3 inflammasome and subsequent induction of the release of IL-1β exerts a central role in the initiation of gout flares." (PMID 34925366, 2021). "Multiple studies have shown that the deposition of MSU is the major cause of gouty arthritis, and intra-articular injection of MSU in mice led to NLRP3 inflammasome-dependent arthritis." (PMID 34512673, 2021). "We intended to search and develop a new pharmacological inhibitor of the NLRP3 inflammasome for the prevention of gout inflammation." (PMID 33670601, 2021). "Sex elements affect gout flare by regulating NLRP3 inflammasome activation and ATP-P2X7R-NLRP3 pathway." (PMID 34150848, 2021). "In continuation with our previous work, the present study demonstrated the TF from S. moellendorffii exerted its anti-gout activity by inhibiting the NLRP3/ASC/Caspase-1 pathway." (PMID 34079466, 2021). "The potent ethnopharmacological properties of S. moellendorffii make it an excellent natural source of novel medicinal targets for NLRP3 inflammasome-related gout treatment." (PMID 34079466, 2021). "In gout, the IL-1-dependent innate inflammatory phenotype is now known to rely on the formation of the macromolecular NLRP3 inflammasome complex in response to the MSU." (PMID 33519292, 2020). "A Monosodium urate (MSU) and CPPD crystal activate the production of IL‐1β in the nod‐like receptor protein‐3 (NLRP3) inflammasome, resulting in gout and pseudo‐gout attacks." (PMID 32608157, 2020). "Excessive activation of NLRP3 inflammasome contributes to the progress of several immune diseases, such as ulcerative colitis, endotoxic shock and gouty arthritis." (PMID 32656909, 2020). "It has been demonstrated by emerging evidence that a positive correlation exists between the progression of gouty arthritis and NLRP3 inflammasome activation." (PMID 33162822, 2020). "Oridonin also reduced peritonitis, gouty arthritis, and type 2 diabetes in experimental animals by inhibiting NLRP3 activation." (PMID 33101293, 2020). "In this study, we focused primarily on how gallic acid modulates NLRP3 activation, while the in vivo experiments preliminarily identified the ameliorative effect of gallic acid on gouty arthritis." (PMID 33365024, 2020). "In summary, we found that gallic acid suppresses ROS generation, thereby limiting NLRP3 inflammasome activation and pyroptosis dependent on Nrf2 signaling, suggesting that gallic acid possesses therapeutic potential for the treatment of gouty arthritis." (PMID 33365024, 2020). "The microtubule skeleton drug colchicine, as the therapeutic drugs for gout, mitigates the gout flare by inhibiting NLRP3 inflammasome activation." (PMID 32656909, 2020).